DDIT3 (DNA damage inducible transcript 3)
Diseases named in the same sentence as DDIT3 in open-access papers (continued):
Sharing a sentence is not in itself a finding about the gene and the disease.
infection (122 papers, 2006 to 2025). The state of being infected such as from the introduction of a foreign agent such as serum, vaccine, antigenic substance or organism. "The PERK branch of UPR-associated genes, including ATF4, ATF5 CHAC1, PDI, and DDIT3, were upregulated upon infection." (PMID 35368019, 2022). "In this light, increased GAS5, TBL2, ATF4, and DDIT3 would be explained as related to cell stress upon infection." (PMID 36768954, 2023). "Ddit3-/- mice exhibited a 56% reduction in infection (1,416,227 ± 44,850; total peak area ± standard error) compared to control mice (3,189,123 ± 69,887; unpaired t test, p<0.001; n = 4 mice per group)." (PMID 34866573, 2021). "In primary NHBE cells, pre-infection priming with TG enhanced expression of the ER stress genes (DDIT3, HSPA5 and HSP90B1), relative to the DMSO control, before and during RSV infection in a TG dose-dependent manner." (PMID 33546185, 2021). "C. parvum infection of Ddit3-/- mice resulted in a 56% reduction in the area under the curve compared to infection in C57BL/6J control mice (3,189,123 ± 69,887, 1,416,227 ± 44,850; total peak area ± standard error; unpaired t test, p<0.001)." (PMID 34866573, 2021). "Indeed, normalized gene expression from paw tissue revealed greater levels of cytokines and a trend for Hspa5 and Ddit3, suggesting that the paws had a relatively greater burden of infection compared to spleen." (PMID 40366144, 2025). "However, DDIT3 does not degrade MAVS in the presence of BoHV-1 (DNA virus) infection, indicating that DDIT3 inhibits IFN-I in different ways during infection by DNA and RNA viruses." (PMID 35259065, 2022). "To analyze whether overexpression of HMOX1 might induce Ddit3 expression in the unstressed condition, we examined Ddit3 expression in neural retinas 2 weeks after infection with AAV8-HMOX1." (PMID 33691741, 2021). "Interestingly, infection with the Honduras strain (R103451) also induced protein expression of DDIT3/CHOP, which is a member of the CCAAT/enhancer-binding protein (C/EBP) family of transcription factor which is activated by ER stress to promote apoptosis." (PMID 30735502, 2019). "Post-infection, members of the heat shock protein 70 (HSP70) family, specifically HSPA1B, and transcription factors ATF4, DDIT3, and JUNB showed increased expression (p < 0.05)." (PMID 39600797, 2024). "(H) Ddit3-/- and C57BL/6J mice were treated with anti-mouse-IFN gamma antibody 1 day prior to infection with 10,000 MEDLE2-HA-tdNeon oocysts, and again at day 2 of infection." (PMID 34866573, 2021). "WNVKUN infection of SK-N-SH cells strongly suggested the activation of an apoptotic response as indicated by induction of AP-1 (i.e. FOS and JUN) and DDIT3." (PMID 31664929, 2019). "DDIT3 can interact with FOS and JUN, hence its induction further suggests activation of apoptosis by infection." (PMID 31664929, 2019). "The protein kinase RNA-like endoplasmic reticulum kinase (PERK) arm of the UPR was activated, as the expression of both activating transcription factor 4 (ATF4) and CHOP (DDIT3), critical regulators of the pathway, was altered after infection." (PMID 26792742, 2016). "The analysis of RNA-seq data from infections of A549 cells with each virus demonstrated enrichment of ISR-regulated genes, including ATF3, GADD34 (gene name PPP1R15A), and CHOP (gene name DDIT3)." (PMID 39861909, 2025). "Interestingly, the levels of the CHOP (DDIT3), DR5 (TNFRSF10B), ATF3, and SESN2 proteins were dramatically increased in CYB5R3-overexpressing H1299 and H1703 cells following Ad-CYB5R3 infection." (PMID 38253797, 2024). "Known NMD substrates related to cell stress (Growth Arrest Specific 5, GAS5; transducin beta-like 2, TBL2; and DNA damage-inducible transcript 3, DDIT3) were increased in infected cells, possibly as a result of alterations in the NMD pathway and of a direct effect of the infection." (PMID 36768954, 2023).
infection (continued). "WB data showed that after 2 weeks of infection, AAV8-GFP or AAV8-HMOX1 correspondingly induced high expression of GFP (4.73 ± 1.01fold, n = 3) or HMOX1 (5.26 ± 1.52 fold, n = 3) in both Ddit3+/+ and Ddit3−/− neural retinas." (PMID 33691741, 2021). "Cells with the largest intracellular DENV abundance show little change in the expression of apoptosis effector genes such as caspases, while their upstream regulators such as DDIT3 and TRIB3 are clearly overexpressed during late infection, in line with a prior report (Peña and Harris, 2011)." (PMID 29451494, 2018). "Interestingly, only EDEM1, which is involved in the clearance of misfolded proteins, was transiently up-regulated at day 1 and day 2 post-infection, whereas BiP, DDIT3 and ATF4 mRNA expression were not affected." (PMID 34224022, 2021). "Interestingly, the expression of the DDIT3 (DNA damage-inducible transcript 3) gene, coding for the C/EBP homologous protein (CHOP), which is involved in the unfolded protein response downstream to ATF4, was significantly higher at 9 h post-infection compared to the previous time points." (PMID 36768954, 2023).
neurodegenerative disease (27 papers, 2011 to 2025). A disorder of the central nervous system characterized by gradual and progressive loss of neural tissue and neurologic function. "However, DDIT3−/− cells are resistant to ER stress mediated apoptosis and this is reflected in animal models of cell stress associated degenerative diseases." (PMID 22496745, 2012). "While a prolonged, strong UPR activation mediates apoptosis by activating DNA damage-inducible transcript 3 (DDIT3), mild stress renders protection in neurodegenerative disease models." (PMID 26694419, 2015).
cardiovascular diseases (4 papers, 2012 to 2024). "As a key regulator of endoplasmic reticulum stress, DDIT3 is also reported to be involved in the ROS-dependent ferroptotic process, but its role in the pathological process of cardiovascular disease still remains unknown." (PMID 34262953, 2021).
DDIT3 also shares sentences with these, for which no sentence is quoted: lymphoma (76 papers); diffuse large B-cell lymphoma (60); Hyperglycemia (41); neuroblastoma (33); B-cell lymphoma (22); cardiac hypertrophy (22); Insulin resistance (20); type 2 diabetes (20); Ewing sarcoma (18); Cognitive impairment (16); colitis (16); myocardial infarction (16); depression (13); metabolic disorders (13); non-small cell lung carcinoma (13); Burkitt lymphoma (12); follicular lymphoma (12); non-Hodgkin lymphoma (12); synovial sarcoma (12); endothelial dysfunction (11); kidney disease (11); metabolic syndrome (11); acute kidney injury (10); acute myeloid leukemia (9); injury (9); liver disease (9); nonalcoholic steatohepatitis (9); alveolar rhabdomyosarcoma (8); kidney (8); peripheral neuropathy (8).
A further 330 diseases each share a sentence with DDIT3 in 8 papers or fewer.